OLIG2 (oligodendrocyte transcription factor 2)
Diseases named in the same sentence as OLIG2 in open-access papers (continued):
Sharing a sentence is not in itself a finding about the gene and the disease.
Stroke (17 papers, 2012 to 2025). Sudden impairment of blood flow to a part of the brain due to occlusion or rupture of an artery to the brain. "In the stroke core, 1.3% of cells were double positive for HuNu and Olig2 in the NPCacute group, whereas only 0.5% were HuNu/Olig2‐positive in the NPCdelayed group (p = 0.057)." (PMID 40407281, 2025). "We additionally co‐stained with HuNu and Olig2 antibodies to determine oligodendrocyte differentiation of transplanted NPCs in the ischemic border zone and in the stroke core region." (PMID 40407281, 2025). "Ectopic MBP expression was detected around OLIG2+ cell bodies close to the injury in stroke animals." (PMID 37236198, 2023). "Immunohistochemical analysis showed more OLIG2+ cells in the middle part of the corpus callosum in animals subjected to stroke compared with sham-treated animals." (PMID 37236198, 2023). "In assessment of oligodendrogenesis and cell death, quantification of OPC counts (NG2+Olig2+), proliferative OLs (Ki67+Olig2+), and apoptotic OLs (Caspase3+Olig2+) were conducted at baseline (naïve), and 3–28-day post-stroke in the CC of WT and cKO brains." (PMID 35017668, 2022). "The apoptotic Caspase3+/Olig2+ cells in the WT brains occurred early at 3-day post-stroke (2.8-fold, p < 0.0001) and remained significantly elevated at 28-day post-stroke (2.5-fold, p = 0.0069)." (PMID 35017668, 2022). "It will be important for future studies to dissect out the precise function of these Olig2+ astrocytes in different disease states such as Alzheimer’s disease and stroke." (PMID 33618751, 2021). "Interestingly, the cKO brains exhibited transient but delayed apoptosis of the Olig2+ cells at 14 d post-stroke, which were quickly reduced to the baseline level by 28-day poststroke." (PMID 35017668, 2022). "Likewise, Olig‐2, CNPase, and O4 were increased at 7 days after stroke in IL‐2mAb‐treated mice (P < 0.05, P < 0.01, P < 0.05, respectively)." (PMID 30444079, 2019). "Both the number of BCAS1+ oligodendrocytes and Olig2+ oligodendrocytes were significantly elevated in PE rats, compared to MCAO and anti-activin-A rats, suggesting that microglia-associated activin-A in moderate PE stroke-rats promoted OPCs differentiation and oligodendrogenesis." (PMID 36829205, 2023). "At 7 and 14 days after stroke, we analyzed the expression level of white matter differentiation related markers (MBP, Olig2) and oligodendrocyte progenitor cell markers (CNPase, O4) in the lesion cortex of dMCAO mice." (PMID 30444079, 2019). "According to the results, we found that the number of BrdU/Olig2 positive cells in ET-1 group was not evidently different from that in Sham group at 35 days after stroke, but ET-1 + STIM group significantly promoted the proliferation of Olig2 labeled oligodendrocytes (p < 0.001 vs ET-1)." (PMID 39697542, 2024). "In both SCI and stroke, about 75% of the Pdgfra-CreERT-tdT-positive cells in the lesion border zone were Olig2-positive but Gfap-negative and Sox9-negative OPCs." (PMID 38907165, 2024). "As expected, we found that the number of Olig2- and Myrf-positive cells increased in both the nondiabetic and diabetic mice with stroke at 7 and 21 d in peri-ischemic infarction." (PMID 36615583, 2023). "On the other hand, stroke led to a 51.8 % initial decrease of NG2+Olig2+ OPCs in WT brains at 3-day post-stroke, which did not further decline at 14–28-day post-stroke." (PMID 35017668, 2022). "We further characterized the in vivo profile of surviving drNPCs (HuNu+ or STEM121+ cells) at 32 days post-stroke using immunostaining for Sox2 and Nestin (undifferentiated NPCs), GFAP (astrocytes), TUJ1 (immature neurons), NeuN (mature neurons), and Olig2 (oligodendrocytes)." (PMID 30747366, 2020). "To investigate stroke‐induced changes in pan‐lactylation across different brain cell types, we performed immunofluorescence co‐staining of pan‐Kla with markers of neurons (MAP2 or NeuN), astrocytes (GFAP or S100β), microglia (IBA1), and oligodendrocytes (Olig2 or MBP)." (PMID 40271828, 2025).
malignant glioma (12 papers, 2009 to 2023). A grade III or grade IV glioma arising from the central nervous system. "A recent study has reported that Olig2 critically regulates replication competence in neural stem cells and malignant glioma: for example, loss of Olig2 resulted in a dramatic reduction of neural stem cell proliferation." (PMID 19772605, 2009). "The fact that expression of GFAP and OLIG2 was encountered in older patients harboring SHH-1A and SHH-1B represents a diagnostic pitfall that needs to be considered in the differential diagnosis of malignant gliomas in children and young adults." (PMID 35501487, 2022). "Olig2 is known as a key transcription factor that promotes tumor growth in malignant glioma." (PMID 33833342, 2021). "Although TP mice had a lower malignant glioma penetrance, we observed a significant decrease of Ki67+DCX+mCherry+ cells and an increase of Ki67+OLIG2+mCherry+ cells among total Ki67+mCherry+ cells from T1 to T2." (PMID 33390587, 2021). "Our findings indicate that this regulator of epithelial-mesenchymal transition orchestrates key features of cancer stem cells in malignant glioma and identify ROBO1, OLIG2, CD133 and MGMT as novel targets of the ZEB1 pathway." (PMID 23818228, 2013).
medulloblastoma (11 papers, 2019 to 2024). A malignant, invasive embryonal neoplasm arising from the cerebellum. "Conversely, Olig2 or GFAP positivity should only be found in a small number of cells in medulloblastomas." (PMID 38201659, 2024). "OLIG2-expressing stem cells have been shown to be treatment-resistant in mouse medulloblastoma models, and to drive recurrence." (PMID 34021242, 2021). "For example, Olig2 is expressed in medulloblastoma samples by tumor stem cells and by oligodendrocytes." (PMID 34021242, 2021). "Recently, Olig2 was shown to increase in recurrent medulloblastoma after radiation therapy and in drug-resistant regions." (PMID 33833342, 2021). "We selected Olig2 for further study because recent functional genetic studies have shown that Olig2+ tumor cells in medulloblastoma are cancer stem cells that play an important role in medulloblastoma initiation and recurrence." (PMID 34021242, 2021). "Stem cell-triggered medulloblastomas progressed faster, contained more OLIG2-expressing stem-like cells, and consistently showed radioresistance." (PMID 34021242, 2021). "We profiled Tuj1 expression, in addition to the stem markers Nestin, Olig2 and Sox2 across a panel of 46 medulloblastomas." (PMID 31160565, 2019). "OLIG2+ progenitors from the glial lineage initiate tumors during the carcinogenesis and relapse of medulloblastoma, indicating that oncogenic networks driven by OLIG2 might be therapeutic targets." (PMID 35574421, 2022). "The importance of Olig2+ medulloblastoma stem cells was shown in prior studies where targeting the Olig2+ population, either by conditional ablation of Olig2-expressing cells using HSV TK or conditional genetic deletion of the Olig2 locus, reduced the growth of SHH-driven medulloblastomas in mice." (PMID 34021242, 2021). "Co-immunohistochemistry/in situ hybridisation investigations for oligodendrocyte markers identified no co-labelling with the mature oligodendrocyte marker CNPase or the glial progenitor cell marker Olig2+ in both wild type and Ptch1lox/lox;GFAPcre medulloblastoma." (PMID 30657775, 2019).
demyelination (8 papers, 2013 to 2024). "Indeed, Fin administration significantly reduced the density of Olig2+ cells in the vicinity of the demyelination lesion (Lyso-Vehicle: n = 4, Lyso-Fin: n = 5, p < 0.001)." (PMID 31118452, 2019). "In the chronic model of cuprizone-induced demyelination, the regeneration process is known to be incomplete; indeed, we observed an inability to catch up control levels in myelin content and Olig2 cell density even 8 weeks after cuprizone removal." (PMID 26142314, 2015). "In contrast, the recruitment of progenitors starts already during the cuprizone diet as indicated by the increase of OLIG2 or NOGOA positive oligodendroglial cells during late stages of cuprizone induced demyelination and as described by Matsushima and colleagues." (PMID 23977356, 2013). "In the DCX reporter model, the numbers of GFP+ cells which were also labeled by Olig2 or Olig2 and CC1 were analyzed after 6 weeks of cuprizone treatment (demyelination group) which were followed by 2 weeks of normal chow (remyelination group) and compared to controls." (PMID 33208869, 2020). "Additionally, overexpression of Olig2, a key transcription factor for OPC fate determination, enhances OPC recruitment to the demyelinated lesions in the corpus callosum of lysolecithin-induced demyelination mouse model and promotes further differentiation." (PMID 39044821, 2024).
cognitive deficits (7 papers, 2016 to 2024). "Olig2 is involved in cell fate of ventral neuroectodermal progenitors and differential expression impaired interneuron differentiation, causing cognitive impairments." (PMID 38637827, 2024). "Among these genes were key transcriptional regulators (e.g., Ahr, Id2, Nr4a1, Nr4a3, Olig2, Zbed4), sustaining previous evidence that several severe cognitive disorders are associated with alterations in transcriptional regulatory activity." (PMID 37048129, 2023). "Of note, several evidence showed that Olig2 deficiency as well as the presence of rare genetic polymorphisms in this gene (i.e., rs1059004) may represent risk factors for cognitive disorders and schizophrenia, through an effect on neuroanatomical connectivity." (PMID 37048129, 2023). "Along the same lines, the ablation of oligodendrocyte transcription factor 2 (Olig2), a transcription factor controlling oligodendrocyte development, resulted in hypomyelination and cognitive deficits in mice." (PMID 37548935, 2024). "OLIG2 can significantly improve memory and cognitive impairment after transient ischemia by increasing oligodendrocyte-specific protein and brain-derived neurotrophic factor expression." (PMID 38221931, 2024). "Proline-rich coiled-coil 2 A (Prcc2a) has been shown to regulate oligodendrocyte transcription factor 2 (Olig2) mRNA stability as an m6A reader, and Prcc2a knockout mice led to motor and cognitive impairments, demyelination, and a shortened lifespan." (PMID 37762200, 2023). "The widespread effect of Olig1 and Olig2, e.g., overexpression from the early developmental stage, was the main component of the cognitive deficit phenotype in DS." (PMID 33329702, 2020).
ischemia (7 papers, 2014 to 2025). A hypoperfusion of the BLOOD through an organ or tissue caused by a PATHOLOGIC CONSTRICTION or obstruction of its BLOOD VESSELS, or an absence of BLOOD CIRCULATION. "Ischaemia was associated with marked loss of total Olig2-positive oligodendrocytes with reduced density of myelin and linearity of the white matter tracts (P < 0.01), and microglial induction and increased caspase-3-positive apoptosis." (PMID 34409290, 2021). "In the present study cerebral hypothermia started three hours after the end of ischemia and continued for either 3 or 5 days was associated with partial improvement in numbers of Olig-2-positive oligodendrocytes of the intragyral and periventricular white matter." (PMID 27121655, 2016). "Total numbers of (Olig2-positive) oligodendrocytes were significantly reduced in the ischemia-normothermia group compared to sham controls in the intragyral white matter of the 1st and 2nd parasagittal gyri and periventricular white matter (p < 0.05)." (PMID 27121655, 2016). "A similar increase in Shh is found within areas of ischemic stroke, and an inhibition of Smo has been shown to prevent natural recovery, while eliminating Shh has been shown to reduce the number of regionally produced Olig2+ cells during the post-ischemia recuperation process." (PMID 30981282, 2019). "It is worthy to note that F3.Olig2-Shh cells express considerably high level of BDNF which is known for it’s significant neuroprotective function in neurodegenerative diseases, ischemia and brain injury." (PMID 24844281, 2014).
demyelinating disease (6 papers, 2013 to 2026). A broad group of disorders that affect the myelin sheaths that cover the neurons. "Thus, OLIG2 protein loss may serve as an early indicator of oligodendrocyte stress and a possible therapeutic target for preserving myelin integrity in demyelinating disorders." (PMID 41876812, 2026). "Better understanding of Shh and Olig2 function in human OL development is a critical point in developing new therapeutic targets for demyelinating diseases." (PMID 24379757, 2013). "The current study demonstrates the effective role of transcriptional regulators (OLIG2 and MYT1L) as a remarkable tool for stimulating myelin repair in lethal demyelinating disorders using cell-based therapeutic approach." (PMID 37232730, 2023).
Down syndrome (6 papers, 2015 to 2024). "Olig1 and Olig2 triplication is associated with developmental brain defects in Down syndrome." (PMID 26035870, 2015). "Our study found ATP5O, DYRK1A, MRAP and OLIG2 have high burden in AVSD, especially DYRK1A that is highly and dynamically expressed in the developing heart, and the gain of function rather loss of function of it will leads to AVSD and Down’s syndrome phenotype." (PMID 36816019, 2023).
neuroblastoma (6 papers, 2014 to 2024). Neuroblastoma (NB) is the most common solid, extracranial childhood tumor. "Indeed, pathological features can overlap between embryonal tumor subtypes, particularly those with BRD4::LEUTX fusions and FOXR2-activated neuroblastomas; most notably the small poorly differentiated cells, abundant necrosis, and co-expression of immunomarkers synaptophysin and OLIG2." (PMID 38500181, 2024). "By 5 days in 3D cultures, neuroblastoma cells in collagen gels showed up-regulation of neuronal markers and PROM1 (CD133, prominin) and slight down-regulation of glial markers (e.g. OLIG2 and GFAP) in 3D as compared to 2D." (PMID 32321995, 2020).
Alzheimer disease (5 papers, 2010 to 2025). A progressive, neurodegenerative disease characterized by loss of function and death of nerve cells in several areas of the brain leading to loss of cognitive function such as memory and language. "Under brain injury and disease conditions such as Alzheimer’s disease and ischemic stroke, Olig2 is robustly upregulated in reactive astrocytes." (PMID 33618751, 2021). "Additionally, the signatures of several transcription factors, such as Olig2, NeuroD1, TCF4, and NeuroG2, were found to be enriched in Alzheimer’s disease-associated accessible chromatin regions within hippocampal tissues." (PMID 40483385, 2025).
brain cancer (5 papers, 2009 to 2022). A primary or metastatic malignant neoplasm affecting the brain. "OLIG2 is expressed only in the central nervous system (CNS) and plays an important role in the development of brain cancers." (PMID 27447975, 2016). "Some of the uniquely expressed genes include CD44 (quantified in FPW1), ERBB2 (quantified in RN1), and OLIG2 (quantified in PB1) and are genes with key roles in brain cancer." (PMID 31973233, 2020). "This is consistent with the fact that Olig2 is not sufficient for brain cancer formation." (PMID 19772605, 2009).
melanoma (5 papers, 2020 to 2025). A malignant, usually aggressive tumor composed of atypical, neoplastic melanocytes. "We show that Olig2 is highly expressed in various melanoma cell lines and contributes to invasive growth of melanoma cells." (PMID 33833342, 2021). "We examined Olig2 localization using western blot analysis of nuclear and cytoplasmic fractions from melanoma cells." (PMID 33833342, 2021). "We demonstrated that Olig2 is associated with MEK/ERK and PI3K/AKT signaling pathways in melanoma cells." (PMID 33833342, 2021). "To examine the mechanism by which silencing of Olig2 suppressed melanoma cell viability, we measured cell apoptosis following Olig2 knockdown." (PMID 33833342, 2021). "To identify the roles of Olig2 in melanoma, we used a CRISPR/Cas9 system to precisely create a loss-of-function mutation in the Olig2 gene." (PMID 33833342, 2021). "Taken together, these findings indicate that reduction in Olig2 induces apoptosis in melanoma cells." (PMID 33833342, 2021). "Further in vivo studies are necessary to confirm the roles of Olig2 in metastatic progression of melanoma." (PMID 33833342, 2021). "In conclusion, this study is the first to investigate the molecular mechanism of Olig2 in melanoma cells." (PMID 33833342, 2021). "We further investigated the mechanistic roles of Olig2 in melanoma invasion through the expression of EMT markers." (PMID 33833342, 2021). "Next, we examined cell viability after transfection of CRISPR-Olig2 to examine the role of Olig2 in melanoma survival." (PMID 33833342, 2021). "To investigate the clinical significance of Olig2 in melanoma tissue, we analyzed published microarray data of Olig2 from the GSE7553 data set." (PMID 33833342, 2021). "For example, a recent study discovered upregulation of Olig2 in melanoma." (PMID 37274223, 2023). "We found that reduction of Olig2 in melanoma cells inhibited the expression of Bcl-2." (PMID 33833342, 2021). "Olig2 predominantly localized in the nucleus in both A375 and 501mel melanoma cells." (PMID 33833342, 2021). "We analyzed the role of Olig2 in apoptosis, migration, and invasion of melanoma cells." (PMID 33833342, 2021). "When Olig2 level was decreased, caspase-3/-7 activity increased in melanoma cells." (PMID 33833342, 2021). "Olig2 staining was higher in stage 2 and 3/4 melanoma tissue compared with normal skin tissue." (PMID 33833342, 2021). "Reduction of Olig2 induced apoptosis of both A375 and 501mel melanoma cells." (PMID 33833342, 2021). "Our results suggest that Olig2 control EMT-like process in melanoma cells." (PMID 33833342, 2021). "In conclusion, this study demonstrated the crucial roles of Olig2 in apoptosis, migration, and invasion of melanoma and may help to further our understanding of the relationship between Olig2 and melanoma progression." (PMID 33833342, 2021). "To investigate whether Olig2 regulates migration of melanoma cells, we evaluated cell migration using an in vitro scratch assay." (PMID 33833342, 2021). "To determine whether Olig2 regulates MITF expression, we inhibited Olig2 in two melanoma cells and then identified the protein expression of MITF by immunoblotting." (PMID 33833342, 2021).